SOST (sclerostin)
Diseases named in the same sentence as SOST in open-access papers (continued):
Sharing a sentence is not in itself a finding about the gene and the disease.
kidney damage (2 papers, 2021 to 2023). "We further investigated whether PMWCNT-induced kidney damage could affect bone mineral metabolism and vascular calcification, which are major categories of aging, using related serum proteins including DKK-1, FGF-23, and sclerostin." (PMID 37112600, 2023).
knee osteoarthritis (2 papers, 2021 to 2026). "In our patient cohort with mild-to-moderate knee osteoarthritis (OA), sclerostin, osteoprotegerin (OPG), and receptor activator of nuclear factor kappa-B ligand (RANKL) were not related to pain or disease activity." (PMID 41828444, 2026). "It is speculated that SOST may have nothing to do with cartilage destruction in knee osteoarthritis, or there are other compensation molecules in the cartilage, so the effect of SOST inhibition is masked." (PMID 34901023, 2021). "There was no significant change in the expression of SOST in the bone tissue of patients with knee osteoarthritis." (PMID 34901023, 2021).
long bone fracture (2 papers, 2024). "In conclusion, with this analysis we can provide preliminary results on the dynamics of DKK1 and SOST after human traumatic long bone fracture." (PMID 38499638, 2024). "Additionally, sclerostin (SOST), a glycoprotein mainly produced by osteocytes, and circulating Dickkopf-1 (DKK1) dynamics were recently evaluated in patients after a traumatic long bone fracture." (PMID 38673606, 2024).
Parkinson disease (2 papers, 2024 to 2025). A progressive degenerative disorder of the central nervous system characterized by loss of dopamine producing neurons in the substantia nigra and the presence of Lewy bodies in the substantia nigra and locus coeruleus. "Another study selected 50 Parkinson’s disease patients undergoing peritoneal dialysis (PD) to investigate the relationship between Sclerostin levels and arterial stiffness." (PMID 38714960, 2024).
Peri-Implantitis (2 papers, 2022 to 2024). An inflammatory process with loss of supporting bone in the tissues surrounding functioning DENTAL IMPLANTS. "The PICF values of sclerostin and RANKL, which are biomarkers associated with bone resorption, showed significant reduction following peri-implantitis treatments in both groups." (PMID 39080143, 2024). "Furthermore, the findings suggest that IL-17, sclerostin and IL-1β may serve as promising biomarkers for assessing efficacy of peri-implantitis treatment." (PMID 39080143, 2024). "Two clinical studies collecting gingival crevicular fluid of patients with implants showed that the sclerostin level is significantly higher around inflamed implants than around healthy implants, suggesting that sclerostin might serve as a valuable biomarker of peri-implantitis." (PMID 35562828, 2022).
polymyalgia rheumatica (2 papers, 2020 to 2024). A syndrome characterized by pain, stiffness, and tenderness of the proximal muscle groups including the shoulder, pelvic girdle and the neck. "Currently, data on bone turnover markers (BTM) in polymyalgia rheumatica are scarce, and data on the profile of Dkk-1, sclerostin, and the changes of bone metabolism induced by GC are completely lacking." (PMID 33015101, 2020).
primary biliary cholangitis (2 papers, 2020 to 2025). Primary biliary cholangitis (PBC) is a chronic and slowly progressive cholestatic liver disease of autoimmune etiology characterized by injury of the intrahepatic bile ducts that may eventually lead to liver failure. "In a study on patients with primary biliary cholangitis (PBC), local expression of sclerostin in the bile ducts was reported, especially in early stages of the disease but declined in advanced disease stages." (PMID 31912287, 2020).
primary hypertension (2 papers, 2021 to 2024). "The study aimed to assess serum sclerostin concentration and its relationship with blood pressure, arterial damage, and calcium-phosphate metabolism in children and adolescents with primary hypertension (PH)." (PMID 34441870, 2021). "In our cross-sectional single-center study, we analyzed serum sclerostin in the group of pediatric patients with primary hypertension." (PMID 34441870, 2021). "Considering the short duration of the disease and a small number of comorbidities, the population of children and adolescents with primary hypertension seems to be an ideal group to study the relationship between sclerostin, blood pressure, and subclinical arterial damage." (PMID 34441870, 2021). "For example, in pediatric patients with primary hypertension, elevated sclerostin levels are linked with lower systolic blood pressure, whereas in postmenopausal women with nonobstructive CAD, higher sclerostin levels help preserve coronary function despite vascular changes." (PMID 39767786, 2024).
pulmonary hypertension (2 papers, 2024). Increased pressure within the pulmonary circulation due to lung or heart disorder. "This is the first study to suggest that sclerostin is an important link to pulmonary hypertension and has positive relationship with all-cause mortality beyond an altered bone–vascular axis in pre-dialysis ESKD patients." (PMID 38341544, 2024). "In this study of 44 patients with ESKD who were predialysis ESKD PD candidates, we observed that a high sclerostin (≥ 218.18 pmol/L) level was associated with pulmonary hypertension and deleterious echocardiographic parameters." (PMID 38341544, 2024). "Higher serum sclerostin levels were also associated with eccentric myocardial remodeling, a thick myocardium, and pulmonary artery hypertension, with significantly elevated pulmonary artery pressure." (PMID 38341544, 2024). "The median age was 54 ± 15 years (range, 27–91 years), and the median sclerostin patients were divided into two groups according to sclerostin level using a receiver operating characteristic curve to determine the best-associated criterion value of sclerostin with pulmonary hypertension." (PMID 38341544, 2024). "If sclerostin is related to changes in vasculature, it could be possible to expand whether the correlation with pulmonary arterial hypertension can be predicted." (PMID 38341544, 2024). "Thus, sclerostin-mediated attenuation of Wnt activities may contribute to pulmonary hypertension in 45% of T21 patients with CHD and 28% without CHD." (PMID 38828726, 2024).
spinal cord injuries (2 papers, 2019 to 2022). "Serum sclerostin was significantly lower in a group with high levels of physical activity than in a group with low levels of physical activity, whereas sclerostin was higher in patients with paralysis resulting from spinal cord injuries than in those with no injury." (PMID 31164134, 2019).
Spondylarthropathies (2 papers, 2015 to 2023). "In spondyloarthropathy, the significance of sclerostin remains unclear and requires further investigation." (PMID 37834893, 2023).
abscess (1 paper, 2026). An inflammatory process characterized by the accumulation of pus within a newly formed tissue cavity which is the result of a bacterial, fungal, or parasitic infection or the presence of a foreign body. "ROC analysis indicated that GCF sclerostin and GCF PGE2 tests had sufficient diagnostic performance to be used in the diagnosis of abscess formation in AP." (PMID 40323540, 2026). "In the ROC analysis performed for the diagnostic performance of abscess formation in AP, the sensitivity of the GCF sclerostin and GCF PGE2 tests was determined as 65.5% and 72.7%, specificity as 98.6% and 68.6%, and AUC as 0.768 and 0.712, respectively (p < 0.0001)." (PMID 40323540, 2026). "Accordingly, since GCF RANKL, GCF MMP-9, serum sclerostin, and serum PGE2 had AUC values of < 0.70, they were deemed unable to determine abscess formation in AP." (PMID 40323540, 2026). "The results of binary regression analysis that indicated GCF sclerostin and GCF MMP-9 together have a significant effect on AP-related abscess formation is further evidence of a relationship between these two bioactive molecules in terms of bone resorption." (PMID 40323540, 2026). "Both GCF sclerostin and PGE-2 independently showed close relationships with PAI-abscess scores used to determine AP severity and they can be used in combination for diagnosing and monitoring AP-related bone resorption." (PMID 40323540, 2026). "In sum, statistical analysis indicated that GCF sclerostin and GCF PGE2 levels are both closely related to abscess formation in AP and can be used independently to determine the severity of AP and bone resorption identified by PAI." (PMID 40323540, 2026). "For this reason, using sclerostin and PGE2 tests in GCF alone or more effectively together, rather than serum tests, will be useful in the diagnosis and follow-up of bone resorption (abscess formation), which is the severe form of AP." (PMID 40323540, 2026). "In other words, GCF sclerostin and PGE2 levels may be considered to be predictive markers of AP-related abscess formation." (PMID 40323540, 2026). "Regression analysis performed in this study determined that a model consisting of OHI score, GCF sclerostin, GCF MMP-9, and GCF PGE2 tests could predict abscess formation related to AP severity with an accuracy of approximately 80.8%." (PMID 40323540, 2026). "Furthermore, when used in combination, OHI score, GCF sclerostin, GCF MMP-9, and GCF PGE2 levels can predict the severity of AP-related abscess formation with approximately 80.8% accuracy." (PMID 40323540, 2026). "Therefore, longitudinal studies following patients over time will be necessary to determine whether changes in sclerostin, PGE2, RANKL, and MMP-9 levels precede or result in AP severity and abscess formation." (PMID 40323540, 2026). "GCF levels of sclerostin, a powerful inhibitor of bone formation, and PGE2, which regulates many biological responses of cells, including inflammation, pain, and fever, were both shown to have a close relationship with the PAI abscess scores used to determine the severity of AP." (PMID 40323540, 2026).
acute coronary syndrome (1 paper, 2021). Signs and symptoms related to acute ischemia of the myocardium secondary to coronary artery disease. "Nevertheless, at a 9-year follow-up, we proved that sclerostin levels virtually affected prognosis in patients with chronic coronary syndrome, but not in patients with acute coronary syndrome." (PMID 33800939, 2021).
acute promyelocytic leukemia (1 paper, 2023). An aggressive form of acute myeloid leukemia (AML), characterized by arrest of leukocyte differentiation at the promyelocyte stage, due to a specific chromosomal translocation t(15;17) in myeloid cells. "Based on the present data, it would therefore be interesting to measure circulating levels of sclerostin and bone mass in patients with acute promyelocytic leukemia treated with ATRA." (PMID 37239103, 2023).
Adrenal insufficiency (1 paper, 2022). Insufficient production of steroid hormones (primarily cortisol) by the adrenal glands. "Mean serum sclerostin concentration was significantly higher in patients with adrenal insufficiency than in control group (44.7 ± 23.5 vs 30.7 ± 10.4 pmol/l, p=0.006)." (PMID 36407318, 2022). "The bone status in patients with primary adrenal insufficiency was not impaired in comparison to control group, while sclerostin concentration was higher." (PMID 36407318, 2022).
alcohol abuse (1 paper, 2013). The use of alcoholic beverages to excess, either on individual occasions ("binge drinking") or as a regular practice. "Serum sclerostin levels have recently been demonstrated to be significantly elevated in individuals with chronic alcohol abuse where they also correlated with decreased measures of bone turnover." (PMID 24386373, 2013).
alcoholic liver diseases (1 paper, 2020). A disorder caused by damage to the liver parenchyma due to alcohol consumption. "In alcoholic liver disease, low sclerostin concentrations were seen." (PMID 31912287, 2020).
apical periodontitis (1 paper, 2026). "Although all this information shows that the role of sclerostin in bone metabolism is well explained, its specific relationship with apical periodontitis (AP) has not yet been fully emphasized." (PMID 40323540, 2026).
Atherosclerotic lesion (1 paper, 2018). A lesion associated with atherosclerosis, a multifactorial and multipart progressive disease manifested by the focal development within the arterial wall of lesions, that ranges from the development of a fatty streak, plaque progression, and plaque disruption. "In type 2 DM patients with atherosclerotic lesions, serum sclerostin level is also increased." (PMID 30482161, 2018).
autoimmune hypothyroidism (1 paper, 2022). "Similarly, we did not observe significant differences in sclerostin, TBS, BMD between patients with and without the diagnose of autoimmune hypothyroidism." (PMID 36407318, 2022).
autoimmune primary adrenal insufficiency (1 paper, 2022). "Correlations between TBS/densitometry parameters/sclerostin and other clinical characteristics in 29 patients with autoimmune primary adrenal insufficiency." (PMID 36407318, 2022). "In conclusion, we performed the first published study comparing TBS values and sclerostin concentrations between patients with autoimmune primary adrenal insufficiency and healthy controls." (PMID 36407318, 2022). "In this context, the aim of our study was to evaluate TBS and sclerostin serum concentrations in patients with autoimmune primary adrenal insufficiency." (PMID 36407318, 2022).
Brain atrophy (1 paper, 2023). Partial or complete wasting (loss) of brain tissue that was once present. "The objective of the present study is to analyze the prevalence of vascular calcifications in alcoholics, and the relationships of these lesions with brain atrophy, as well as the role of sclerostin on these alterations." (PMID 36895513, 2023). "Logistic regression analyses disclosed that sclerostin was the only variable independently related to brain atrophy assessed by altered cella media index." (PMID 36895513, 2023). "Interestingly in addition to age, sclerostin was strongly related to vascular calcifications, and it was also independently related to brain atrophy, underscoring the role of osteokines on vascular disorders, at least in excessive drinkers." (PMID 36895513, 2023). "Therefore, the relationship of sclerostin with brain atrophy is especially marked in patients with vascular calcifications." (PMID 36895513, 2023). "Lastly, the ability of sclerostin in the diagnosis of brain atrophy (cella media index) is even more marked in non-hypertensive patients with vessel wall calcium deposits." (PMID 36895513, 2023).
Cachexia (1 paper, 2020). Severe weight loss, wasting of muscle, loss of appetite, and general debility related to a chronic disease. "Four were common for local/cachexia (C1R, PRKCG, ELANE, SOST: all oppositely regulated) and four for metastatic/cachexia (SERPINA6, PDGFRA, PRSS2, PRSS1: all consistently changed), suggesting that stage and cachexia status might be molecularly separable." (PMID 33334063, 2020).
cardiac hypertrophy (1 paper, 2023). "This might decrease vascular calcification, decrease vascular stiffness, decrease cardiac hypertrophy, decrease sclerostin production, reduce serum sclerostin and improve skeletal remodeling." (PMID 36776982, 2023).
cerebral palsy (1 paper, 2022). A group of disorders affecting the development of movement and posture, often accompanied by disturbances of sensation, perception, cognition, and behavior. "Patients with nonambulatory (i.e., immobilized) cerebral palsy showed higher sclerostin levels than patients with ambulatory cerebral palsy." (PMID 33738515, 2022).
cervical cancer (1 paper, 2018). A primary or metastatic malignant neoplasm involving the cervix. "Among the genes, SOST is involved in the negative regulation of the Wnt signaling pathway, which is a critical signaling pathway modulating cervical cancer cell proliferation, migration, and angiogenesis." (PMID 30344797, 2018). "Among the potential targeting genes, SOST, MTA1, TFRC, and YAP1 are involved in some important signaling pathways modulating cervical cancer cell invasion, migration, and drug sensitivity." (PMID 30344797, 2018).
cholestasis (1 paper, 2021). Impairment of the bile flow caused by obstruction within the liver, or outside the liver in the bile duct system. "Long-term administration of glucocorticoids in pulmonary disease and multifactorial inhibitory influences on osteoblastic cell function (sclerostin, retained substances of cholestasis, alcohol) are suspected." (PMID 34442036, 2021).
chondroblastoma (1 paper, 2018). A benign, chondroid-producing, well-circumscribed, lytic neoplasm usually arising from the epiphysis of long bones. "In chondroblastoma, the chondroid matrix has been described as “chondrosteoid” by some observers; it has been shown that this matrix contains dentine-matrix protein-1 and sclerostin, proteins found in newly formed osteoid." (PMID 30202513, 2018).
chronic atrophic gastritis (1 paper, 2020). Atrophic gastritis that is persistent and long-standing. "In contrast, a Norwegian study found that, in patients with chronic atrophic gastritis, compared to sex- and age-matched controls, bone formation markers (OC, sclerostin, OPG and OPG/RANKL ratio) were lower and the incidence of OP was higher (the latter abnormality only in males)." (PMID 33053671, 2020).
coronary artery stenosis (1 paper, 2022). "In confounder‐adjusted analyses in LURIC, sclerostin was positively related to CAD severity at study entry, as reflected by Friesinger score and coronary artery stenosis, and with cardiac mortality after follow‐up for a mean of 9.9 years." (PMID 34738659, 2022).
cystinosis (1 paper, 2026). Cystinosis is a metabolic disease characterized by an accumulation of cystine inside the lysosomes, causing damage in different organs and tissues, particularly in the kidneys and eyes. "After kidney transplantation, cystinosis patients demonstrate gradual increases in sclerostin, reflecting improvements in kidney function and bone metabolism." (PMID 40369127, 2026). "In addition, unlike CKD patients who typically exhibit elevated sclerostin levels due to declining renal clearance, patients with cystinosis demonstrate lower sclerostin, particularly in early CKD stages." (PMID 40369127, 2026). "However, despite normalization of renal clearance, persistent skeletal abnormalities suggest that intrinsic osteoblast/osteoclast dysfunction, rather than sclerostin regulation alone, contributes to bone disease in nephropathic cystinosis." (PMID 40369127, 2026).
dental pulp inflammation (1 paper, 2022). "Existing experimental evidence suggests that sclerostin inhibition seems to be promising for anti-inflammation and pro-regeneration during dental pulp inflammation." (PMID 35562828, 2022). "Hence, sclerostin might also participate in the regulation of dental pulp inflammation by promoting the aging process of DPCs." (PMID 35562828, 2022).
developmental dysplasia of the hip (1 paper, 2020). A spectrum of hip abnormalities commonly presenting in infancy involving the relationship between the femoral head and the acetabulum and that includes subluxation or dislocation at rest or upon provocation. "Therefore, we detected the differential expression of POSTN and SOST in BMSCs of SONFH Group patients, and Control Group was patients with traumatic ONFH (TONFH) and developmental dysplasia of the hip (DDH)." (PMID 33409280, 2020).
diabetic angiopathies (1 paper, 2025). "However, limited data exist regarding the association between serum sclerostin levels and diabetic angiopathy in pediatric and adolescent patients with T1DM, highlighting the need for further investigation." (PMID 40353858, 2025).